MYBL2 (MYB proto-oncogene like 2)
Diseases named in the same sentence as MYBL2 in open-access papers (continued):
Sharing a sentence is not in itself a finding about the gene and the disease.
lung adenocarcinoma (continued). "MYB proto-oncogene like 2 (MYBL2) was the highest differentially expressed transcription factor upregulated in RAD51 High lung adenocarcinomas." (PMID 33489883, 2020). "Here, we describe a MYBL2-driven transcriptional program that promotes error-prone double-strand break repair, genomic instability, and poor patient outcomes in lung adenocarcinoma." (PMID 33489883, 2020). "It will be important to examine the efficacy of CHK1 inhibitors in combination with either RAD51 or POLQ small molecules when treating MYBL2 High lung adenocarcinomas." (PMID 33489883, 2020). "Moving forward, our results have important implications for utilizing CHK1-targeted therapies for the future treatment of MYBL2 High lung adenocarcinoma." (PMID 33489883, 2020). "Among the activated transcriptional regulators, CENPA, MYBL2, and FOXM1 were linked to numerous cancer-specific enhancers and high expression of these regulators was observed in a subgroup of lung adenocarcinomas showing poor patient survival." (PMID 32925947, 2020). "Based on current cancer statistics, MYBL2 High lung adenocarcinoma is estimated to represent 21,067 new cases this year alone." (PMID 33489883, 2020). "In this study, we demonstrate that MYBL2 High lung adenocarcinomas upregulate transcriptional programs that coordinate replication stress responses and POLQ-mediated error-prone repair despite containing BRCA proficient pathways." (PMID 33489883, 2020). "Since increased mutations and chromosomal rearrangements are linked with tumor heterogeneity, disease recurrence, and metastasis, we sought to understand the MYBL2-driven programs promoting disease progression in lung adenocarcinoma." (PMID 33489883, 2020). "As expected, we found that MYBL2 High lung adenocarcinomas had significantly higher combined HRD scores (p = 2.22e–30)." (PMID 33489883, 2020). "Taken together, these data confirmed that MYBL2 High lung adenocarcinomas exhibited a novel genomic instability phenotype with inefficient HR in the presence of highly expressed, wildtype BRCA1/2." (PMID 33489883, 2020). "MYBL2 High disease not only constitutes one of the most aggressive subtypes of lung adenocarcinoma but it also encompasses a large cohort of patients (~21% of all lung adenocarcinoma)." (PMID 33489883, 2020). "Using robust omics data from two independent studies, we provide evidence that a large cohort of lung adenocarcinomas exhibit significant genome instability and overexpress the DNA damage responsive transcription factor MYB proto-oncogene like 2 (MYBL2)." (PMID 33489883, 2020). "Additional support for prexasertib as a clinical trial agent for MYBL2 High lung adenocarcinomas is provided by a Phase 2 clinical trial recently carried out in high grade serous ovarian cancer (HGSOC)." (PMID 33489883, 2020). "Next, we assessed potential treatment options for lung adenocarcinoma targeting MYBL2 and FOXM1." (PMID 36291764, 2022). "Interestingly, we also found that MYBL2 protein level in nuclear extracts was also reduced upon FDI-6 treatment in A549 lung adenocarcinoma cells." (PMID 36291764, 2022). "Furthermore, we showed that FDI-6 alters cell proliferation and inhibits the activities of FOXM1 as well as MYBL2 in lung adenocarcinoma cells." (PMID 36291764, 2022).
lung adenocarcinoma (continued). "In this study, we characterized the molecular functions of MYBL2 in lung adenocarcinoma cells." (PMID 36291764, 2022). "Using a knockdown experiment of MYBL2 and global transcriptome profiling, we identified that over a thousand genes are dysregulated by MYBL2, and MYBL2 acts as a transcriptional activator in lung adenocarcinoma cells." (PMID 36291764, 2022). "Moreover, by using MYBL2 ChIP-seq and knockdown experiments coupled with RNA-seq, we showed that MYBL2 acts as a transcriptional activator in lung adenocarcinoma cells." (PMID 36291764, 2022). "Moreover, we found that a previously reported FOXM1 inhibitor, FDI-6 (forkhead domain inhibitor 6), suppresses lung adenocarcinoma cell proliferation by inhibiting the activities of MYBL2 and FOXM1 and controlling cell death and cell cycle genes." (PMID 36291764, 2022). "MYB proto-oncogene Like 2 (MYBL2) was known as a transcription factor in lung adenocarcinoma." (PMID 34353336, 2021). "Importantly, a separate analysis of only Stage III and IV lung adenocarcinoma confirmed that patients with MYBL2 High tumors had significantly worse OS outcomes compared to patients with MYBL2 Low tumors (log-rank p = 7.9e–3)." (PMID 33489883, 2020). "Given the low RPS values in MYBL2 High lung adenocarcinomas, we hypothesized that MYBL2 directly upregulated genes that antagonized HR and promoted error-prone DNA repair." (PMID 33489883, 2020). "Thus, inhibitors such as prexasertib, which effectively target both CHK1 and CHK2 would be predicted to be effective therapeutic options for MYBL2 High lung adenocarcinomas." (PMID 33489883, 2020). "While MYBL2 High lung adenocarcinomas show evidence of elevated MMEJ, it is worth pointing out that these are conservative estimates observed at the genome-wide level and the actual level of genomic alterations facilitated by dysregulated MMEJ would be predicted to be even higher." (PMID 33489883, 2020). "Given the association between RAD51 and MYBL2 expression, we examined whether stratifying lung adenocarcinomas on MYBL2 mRNA expression alone could predict OS and DFS outcomes." (PMID 33489883, 2020). "However, MYBL2 has shown the ability to induce proliferation and cell cycle in lung adenocarcinoma." (PMID 36101460, 2022). "Additionally, we observed that FDI-6 could suppress the MYBL2 protein level in A549 lung adenocarcinoma nuclei." (PMID 36291764, 2022). "The results revealed that MYBL2, CENPA, FOXM1, E2F1, ZNF367, and HMGA1 are the most relevant upstream transcription factors in lung adenocarcinoma." (PMID 40885709, 2025). "MYBL2 has been related to the proliferation and migration of NSCLC cells, as well as genomic instability in lung adenocarcinoma." (PMID 36661515, 2023). "MYBL2 and FOXM1 were related to cancer-specific enhancers, and its high expression in lung adenocarcinomas has been related to poor patient survival." (PMID 36661515, 2023). "Overall, our findings suggest that MYBL2 and FOXM1 activate cell cycle genes together, acting as oncogenic transcription factors in lung adenocarcinoma cells, and they are potential treatment targets for the disease." (PMID 36291764, 2022). "For example, we showed that CENPA is one of the key targets of MYBL2 and FOXM1 in lung adenocarcinoma cells." (PMID 36291764, 2022). "Our results demonstrated that MYBL2 and FOXM1 cooperatively regulate the G2/M phase transition cell-cycle genes in lung adenocarcinoma cells." (PMID 36291764, 2022). "Most of the genes were significantly reduced by the knockdown of both MYBL2 and FOXM1 in A549 and NCI-H2126 lung adenocarcinoma cells." (PMID 36291764, 2022). "In this study, we performed MYBL2 and FOXM1 ChIP-seq, identifying global binding sites of MYBL2 and FOXM1 in lung adenocarcinoma cells for the first time." (PMID 36291764, 2022). "To target the oncogenic activities of MYBL2 and FOXM1 in lung adenocarcinoma, we have explored ways to suppress them using an inhibitor." (PMID 36291764, 2022).
lung adenocarcinoma (continued). "Further studies to characterize the mechanisms of MYBL2 and FOXM1 target genes and to determine the effectiveness of FDI-6 in lung adenocarcinoma patients are needed." (PMID 36291764, 2022). "We further examined the expression levels of the identified MYBL2 and FOXM1 target genes in lung adenocarcinoma tissues and adjacent normal lung tissues using TCGA RNA-seq datasets." (PMID 36291764, 2022). "In accordance with the previous finding that MYBL2 and FOXM1 control genes expressed in the G2/M phase of the cell cycle, we found that MYBL2 and FOXM1 regulate genes belonging to the G2/M phase in lung adenocarcinoma cells." (PMID 36291764, 2022). "By integrating the ChIP-seq data with RNA-seq data generated upon the knockdown of MYBL2 and FOXM1, we revealed that MYBL2 and FOXM1 act as transcriptional activators in lung adenocarcinoma." (PMID 36291764, 2022). "We demonstrated that FDI-6 decreases the proliferation of lung adenocarcinoma cells and inhibits the activities of FOXM1 as well as MYBL2." (PMID 36291764, 2022). "Subsequent survival analyses confirmed that overexpression of MYBL2 outperformed both E2F1 and FOXM1 transcription factors in identifying lung adenocarcinoma patients with poor outcomes." (PMID 33489883, 2020). "Consistent with MYBL2 High lung adenocarcinomas upregulating CHK1-dependent checkpoint repair pathways, we find that cell lines with increased MYBL2 expression concomitantly upregulate CHK1 protein expression." (PMID 33489883, 2020). "More importantly, it has been discovered that MYBL2 protein interacts with LOXL1-AS1 promoter and promotes the LOXL1-AS1 expression, demonstrating a positive feedback loop of LOXL1-AS1/miR-423–5p/MYBL2 in lung adenocarcinoma." (PMID 39136001, 2024). "By integrating with TCGA lung adenocarcinoma RNA-seq data, we also confirmed that genes whose promoters bound by MYBL2 are expressed higher than those not bound by MYBL2 in lung adenocarcinoma cells." (PMID 36291764, 2022). "However, our results, which show that FDI-6 treatment changes the expression of key genes and proteins involved in the cell cycle, suggest that MYBL2 and FOXM1 are potential treatment targets for lung adenocarcinoma." (PMID 36291764, 2022). "In addition to CENPA, we identified additional potential target genes of MYBL2 and FOXM1 in lung adenocarcinoma." (PMID 36291764, 2022). "Moreover, we identified novel downstream targets of MYBL2 and FOXM1 that include key oncogenes such as CENPA in lung adenocarcinoma." (PMID 36291764, 2022). "Taken together, these data identify elevated MYBL2 mRNA expression as a robust predictor of poor outcomes in lung adenocarcinoma, regardless of disease stage." (PMID 33489883, 2020). "Given that MYBL2 High patients have significantly poorer outcomes, we explored the cytotoxic efficacy of small molecule CHK1 inhibitors in MYBL2 High lung adenocarcinoma cells." (PMID 33489883, 2020). "To this end, we developed an RNA-based tumor profiling panel that distinguishes MYBL2 High lung adenocarcinomas across both TCGA and ORIEN cohorts, regardless of disease stage." (PMID 33489883, 2020). "However, it is not clear how the MYBL2 transcription factor regulates genes and leads to carcinogenesis in lung adenocarcinoma." (PMID 36291764, 2022). "To study the molecular mechanisms of MYBL2 in lung adenocarcinoma cells, we first investigated MYBL2 expression levels in normal alveolar epithelial cells (AEC), airway epithelial cells, lung fibroblast cells (IMR-90, AG04450), and lung adenocarcinoma cells (A549)." (PMID 36291764, 2022). "In a study on lung adenocarcinoma, four fusion genes (WISP1, RAMP1, MYBL2, and GATA2) of the human leukocyte antigen (HLA) family were identified by RNA-seq technology, indicating that the HLA family genes might be potential targets for the lung adenocarcinoma therapy." (PMID 32117438, 2020).
colorectal cancer (21 papers, 2016 to 2025). A primary or metastatic malignant neoplasm that affects the colon or rectum. "Previous studies have demonstrated that MYBL2 directly transcriptionally regulates RRM2 expression in colorectal cancer cell lines." (PMID 40885709, 2025). "Through Cox multivariate regression analysis of the prognosis of colorectal cancer patients, MYBL2 protein expression and tumor stage were seen to be independent prognostic factors." (PMID 35664780, 2022). "In addition, MYBL2 has also been reported to activate the PI3K/AKT pathway in colorectal cancer cells and non-small cell lung cancer cells." (PMID 39613162, 2024). "We observed that, similar to the regulation of DNA repair genes, MYBL2 expression was regulated by Wnt signaling in AsPC‐1 orthotopic xenografts, as well as in a pancreatic cancer PDX with an RNF43 mutation, and a colorectal cancer PDX with an R‐spondin translocation." (PMID 33660437, 2021). "Similar to previous studies, MYBL2 can regulate tumor progression by regulating CELL CYCLE signaling pathway in esophageal squamous cell carcinoma and colorectal cancer." (PMID 34631522, 2021). "Interestingly, a study has indicated that MYBL2 directly binds to the RRM2 promoter and promoted its transcription in colorectal cancer cells." (PMID 40885709, 2025). "In this study, through searching in cancer-omics databases and immunohistochemistry validation with clinical samples, we showed that the expression of MYBL2, a key oncogenic transcriptional factor, was significantly upregulated correlatively with RRM2 in colorectal cancer (CRC)." (PMID 34234118, 2021).
glioma (21 papers, 2017 to 2025). A benign or malignant brain and spinal cord tumor that arises from glial cells (astrocytes, oligodendrocytes, ependymal cells). "In this study, we found an association between the MYBL2 gene and the expression levels of multiple genes related to cell cycle and DNA replication in glioma patients." (PMID 30305611, 2018). "Our work is the first to reveal that T-96 inhibits glioma growth by inhibiting DNA replication and causes G1/S cell cycle arrest by downregulating MYBL2." (PMID 30305611, 2018). "We also demonstrated the existence of a significant association between MYBL2 and FoxM1 expression in glioma." (PMID 28784180, 2017). "MYBL2 and FoxM1 expression are significantly associated with clinical stages and overall survival of glioma patients." (PMID 28784180, 2017). "In the present study, for the first time, we found that MYBL2 and FoxM1 are significantly associated with glioma progress; meanwhile, MYBL2 is interacted with radiotherapy for glioma survival." (PMID 28784180, 2017). "And, the role of MYBL2 and FoxM1 in glioma cell progression and the underlying mechanisms were studied by using small interfering RNA (si-RNA) and pcDNA3.1 + HAvectors." (PMID 28784180, 2017). "To further confirm the association of MYBL2 and FoxM1 with glioma risk, we analyzed the gene expression data of glioma cases in the high-grade glioma (HGG) TCGA data set, which includes 567 glioma tissues and 10 non-tumor tissues." (PMID 28784180, 2017). "Results of GSEA analysis revealed that MYBL2 may promote the proliferation of glioma-associated fibroblasts." (PMID 38577605, 2024). "MYBL2 may promote the proliferation of glioma-associated fibroblasts and TUBA1C had a high expression in M2 macrophages, which confirms and expands on the results of previous studies." (PMID 38577605, 2024). "MYBL2 was mainly expressed in tumor cells and glioma-associated fibroblasts." (PMID 38577605, 2024). "Furthermore, it has been demonstrated in TCGA glioma patient cohorts that FOXM1 and MYBL2 expression are linked in gliomas." (PMID 35409080, 2022). "MYBL2, GNG10, and AHNAK2 exhibited an elevated gene expression in recurrent gliomas, suggesting involvement in cancer progression (e.g., MYBL2 p = 5.5 × 10−6)." (PMID 39684661, 2024). "MYBL2 has also been proved to be associated with poor prognosis of cancer by pan-cancer analysis, and some literatures have shown that MYBL2 can be upregulated by activation of Akt/FoxM1 to promote the development of glioma." (PMID 36133745, 2022). "The knockdown of MTDH would inhibit the expression of MYBL2 through decreasing the expression of FoxM1 and further reduce glioma cell proliferation and cell migration and invasion." (PMID 36133745, 2022). "Relevant studies have shown that MYBL2 is a key downstream factor of the Akt/FoxM1 signaling pathway in promoting human glioma progression and can be used as a new candidate gene for glioma molecular targeted therapy and a biomarker for radiotherapy." (PMID 36133745, 2022). "The researchers found that Akt/FoxM1 (Forkhead box M1) signaling pathway-mediated up-regulation of MYBL2 (MYB-related protein B2) fosters progression of human glioma." (PMID 35935338, 2022). "Akt/Fox M1 signaling pathway-mediated MYBL2 upregulation promotes the progression of human glioma and is a probable candidate gene for molecular targeted therapy and a biomarker for glioma-related radiation therapy." (PMID 36052073, 2022). "The results showed that MTDH and MYBL2 were overexpressed in glioma cells compared with normal cells." (PMID 36133745, 2022). "Subsequently, we evaluated the prognostic accuracy of CCNB2, CDC20 and MYBL2 by calculating the time‐dependent ROC, AUC (area under the ROC curve) for one‐, three‐ and five‐year survival in glioma patients." (PMID 32696617, 2020).